C2orf92 (chromosome 2 open reading frame 92)
Synonyms: LINC01125
Gene: Protein-coding gene on chromosome 2 (97,664,217 to 97,703,066, forward strand). Ensembl gene ENSG00000228486.
Subcellular location: Membrane
Gene Ontology:
Cellular component: membrane
Homologues: Orthologues: chimpanzee C2orf92 (97% identical), macaque C13H2orf92 (88% identical), rabbit C2orf92 (54% identical), dog C2orf92 (51% identical), mouse 4933424G06Rik (37% identical), rat C9h2orf92 (37% identical).
Diseases named in the same sentence as C2orf92 in open-access papers:
C2orf92 is named in the same sentence as 3 diseases in open-access papers, as found by Europe PMC text mining. Sharing a sentence is not in itself a finding about the gene and the disease.
C2orf92 shares sentences with these, for which no sentence is quoted: breast carcinoma (1 paper); breast tumor (1); tumor (1).